MGMT (O-6-methylguanine-DNA methyltransferase)
Diseases named in the same sentence as MGMT in open-access papers (continued):
Sharing a sentence is not in itself a finding about the gene and the disease.
tumor (continued). "While working on a study about GBM and their matched recurrences, we observed a change of MGMT promoter methylation from primary tumor to relapse in some of the GBM patients." (PMID 31766430, 2019). "In conclusion, for the first time to our knowledge, we report a case of metastasized PC with high tumor MGMT promoter methylation status that benefited from TMZ treatment." (PMID 31044184, 2019). "The tumor had an unmethylated MGMT promotor and the patient underwent conventional radiotherapy of 60 Gy plus concomitant TMZ." (PMID 31780768, 2019). "In summary, both PYR and MSP are reliable methods for detecting MGMT methylation in tumor tissue and can be useful for identifying patients likely to benefit from TMZ." (PMID 31366977, 2019). "It is noteworthy that three out of four patients experiencing tumor recurrence after GTR harbored MGMT promoter methylation." (PMID 31362435, 2019). "The first assessed MGMT promoter methylation by a simple M/U ratio for each tumor specimen (PMR (I))." (PMID 30717206, 2019). "MGMT methylation by PYR-tumor also correlated with outcomes (p = 0.006, p = 0.001, p = 0.005, respectively)." (PMID 31366977, 2019). "MGMT promoter methylation usually is seen as homogenous within the tumor, although some groups reported contrasting results." (PMID 31766430, 2019). "MGMT methylation by MSP-tumor correlated with clinical benefit (p = 0.01), PFS (p = 0.001), and OS (p = 0.001)." (PMID 31366977, 2019). "In the present study, we have assessed MGMT methylation in tumor tissue and in blood by MSP and PYR and compared the reliability of the different analyses." (PMID 31366977, 2019). "One study applied a panel of methylation markers (EYA4, GRIA4, ITGA4, MAP3K14-AS1, and MSC) in 25 patients, and the other measured methylated MGMT in 29 patients with MGMT promoter hypermethylation of tumor tissue." (PMID 31824558, 2019). "Intriguingly, this differential was the greatest in cells expressing the DNA-repair protein MGMT, which is known to confer resistance of tumor cells to treatment with TMZ." (PMID 30651933, 2018). "When the promoters of MGMT are methylated, the resulting O6 lesions will trigger the death of the tumor cells since the transcriptional silencing of the MGMT gene prevents the synthesis of the enzyme that repairs DNA damage inflicted by TMZ." (PMID 30413113, 2018). "A molecular tumor analysis showed almost equal distribution between methylated- and unmethylated-O-6-methylguanine-DNA methyltransferase (MGMT) promoter status (51% and 49%, respectively)." (PMID 30050733, 2018). "It has been shown previously that only 1 out of 50 patient samples had over 50% MGMT-positive cells, and most MGMT-expressed tumor samples have 10–50% MGMT-positive cells." (PMID 30054476, 2018). "As a DNA repair enzyme, decreased MGMT led to severe DNA damage and cell death, eventually more necrosis in tumor." (PMID 29467012, 2018). "On the other hand, a 60% probability of early true tumor progression in unmethylated MGMT promoter tumors was reported." (PMID 30627060, 2018). "The GBM12 xenograft line derived from a newly diagnosed MGMT hypermethylated tumor was used to generate TMZ-resistant sublines." (PMID 30054476, 2018). "Previous studies suggested that MGMT promoter methylation is associated with GBM in parietal and occipital lobes, the left hemisphere and temporal lobe or independent from tumor location." (PMID 29467012, 2018). "The design of PARADIGM-2 aligns with recent clinical trials that have demonstrated the acceptability of omitting temozolomide in patients with MGMT unmethylated tumours." (PMID 29594237, 2018). "In the current study, among all the investigated conventional structural image features, only tumor location and necrosis were correlated with MGMT promoter methylation status." (PMID 29467012, 2018).
tumor (continued). "MGMT is able to remove O6-meG which covalently is attached to the protein and inactivates it9, and emerges as a central determinant of tumor resistance to alkylating agents." (PMID 29426908, 2018). "The relatively low percentage of MGMT-positive cells detected in patient #1 and in 3080 subline is likely due to tumor heterogeneity and/or relatively low sensitivity of MGMT immunofluorescence." (PMID 30054476, 2018). "The GBM46 line is a MGMT low-expressing line from a recurrent tumor, whereas the two MGMT-expressed lines, GBM115 and GBM64, are from primary and recurrent tumor, respectively, and have high levels of MGMT expression." (PMID 30054476, 2018). "The level of MGMT expression is increased when the MGMT gene promoter is unmethylated, which enhances tumor resistance to TMZ." (PMID 29487691, 2018). "The MGMT-mediated repair system is unique in many aspects, consequently making it a difficult task to target MGMT within tumor cells." (PMID 29963012, 2018). "MGMT promoter methylation inhibits the expression of MGMT protein and enhances tumor sensitivity to TMZ." (PMID 30131700, 2018). "MGMT expression increases during tumor progression and correlates with the overall metastatic tumor burden and with the organ/tissue type harboring the metastatic disease." (PMID 30038716, 2018). "On the other hand, if MPG expression and MGMT were both high, the tumor would be highly resistant because all adducts would be repaired." (PMID 29963012, 2018). "The five key variables were MGMT promoter methylation status (MGMT), ADC value (ADC), age, tumor edema (edema), and TERT promoter mutation status (TERT)." (PMID 29984907, 2018). "Future studies should focus on developing therapeutic agents that can work in conjunction with TMZ to suppress the effects of MGMT in tumor cells or to attenuate TMZ resistance." (PMID 29963012, 2018). "The expression level of the MGMT gene was determined by real-time PCR (qPCR) in 32.7% of tumours (n = 17/50)." (PMID 29515653, 2018). "The use of TMZ in the treatment of GBM is limited by the activity of the gene MGMT (O6-methylguanine-DNA methyltransferase) in tumor cells." (PMID 29433556, 2018). "A correlation existed between a higher MGMT expression and greater resistance of the tumor to treatment (the latter reflected in the lower survival of the animals)." (PMID 30583528, 2018). "MGMT methylation status has not been investigated yet, but we are planning to evaluate the biomarkers including MGMT gene expression and methylation using tumor tissues and blood samples." (PMID 29557060, 2018). "As a first conclusion, although numerous GBM cell lines have been published, few of them have been established from tumor cells expressing MGMT transcript and having resistance to TMZ." (PMID 30583471, 2018). "Some studies have reported a change in failure pattern in patients with GBM and 06-methylguanine DNA methyltransferase (MGMT) methylated tumours." (PMID 30029668, 2018). "Based on the immunofluorescence staining, we estimated that the fraction of MGMT-expressing cells increased from 4% in the primary tumor of patient #1 to 24% in recurrent tumor of this patient." (PMID 30054476, 2018). "It is important to accurately evaluate the methylation status of the MGMT gene promoter in clinical decision making for treatment selection and in the development of novel therapies including MGMT silencing by tumor-targeted siRNA delivery." (PMID 29963232, 2018). "As expected TMZ alone drastically reduced tumour growth in animals bearing LN229 tumours which are methylated for MGMT and the combination further reduced luciferase activity to undetectable levels." (PMID 30546006, 2018). "This process is important since the effect of TMZ depends both on the level of MGMT present within the tumor cells, as well as the number of DNA adducts and so, an excess amount of DNA adducts can completely exhaust the MGMT catalytic levels." (PMID 29963012, 2018).
tumor (continued). "A post-hoc analysis of subgroups, however, revealed a trend for improved survival for MGMT unmethylated patients with residual tumor when treated with nimotuzumab (PFS 6.2 vs. 4.0 months; OS 19.0 vs. 13.8 months)." (PMID 30129426, 2018). "The extent of MGMT promoter methylation is different among tumor cells, and normal cells usually contaminate all samples, all of which affect the real-time MSP results." (PMID 29963232, 2018). "The MGMT is a key tumor suppressor gene and aberrant promoter methylation has been reported in many cancers." (PMID 29195029, 2018). "By considering the eight tumors previously treated with TMZ/miR-370-3p, we noted a correlation between the miR-370-induced reduction in tumor volume and the miR-370-induced reduction in MGMT expression." (PMID 30497054, 2018). "The aim of our study was first to characterize this new cell line, named R2J, which expresses the MGMT transcript and exhibits CSC properties associated with in vivo tumor growth, and, second, to evaluate in vitro SS effects." (PMID 30583471, 2018). "Benefit from temozolomide is limited to patients whose tumours exhibit methylation of the MGMT promoter region, and the acceptability of withholding temozolomide from patients with MGMT unmethylated tumours in the context of clinical trials has been validated." (PMID 29594237, 2018). "In this study, we describe the first use of a non-ablative priming dose of ionizing radiation to guide and enhance the delivery of AMONs to downregulate MGMT expression in human tumor cells, both in vitro and in vivo in a rat xenograft tumor model." (PMID 28752860, 2017). "The correlation analysis between the BCAT1 expression level or MGMT promoter methylation status and quantitative values from tumor volumetrics and nCBV and ADC histograms were performed." (PMID 29255149, 2017). "We also confirmed that age, MGMT promoter methylation status, tumor extent, and EOR are significant prognostic factors for survival in GBM patients." (PMID 28682902, 2017). "Evaluation of MGMT promoter methylation status and major genomic alterations in primary tumor samples and the corresponding patient-derived culture pairs revealed consistent findings." (PMID 29088733, 2017). "Future work will extend this analysis by considering tumor location, extent of resection, methylguanine-DNA methyltransferase (MGMT) promoter methylation status, as well as extending this work to other tumor types and anatomical sites." (PMID 29348883, 2017). "Underexpression of MGMT is thought to sensitize tumor cells to temozolomide (TMZ)-based therapies whereas overexpression induces resistance." (PMID 27888622, 2017). "Expressing high levels of MGMT, these cells have been shown to be involved in chemotherapy resistance and responsible for tumor recurrence." (PMID 29225516, 2017). "We therefore conducted a multivariate Cox regression analysis with age, KPS, extent of resection, MGMT promoter methylation and signs for early tumor progression as independent variables." (PMID 28101701, 2017). "On day 30, when all nude mice were sacrificed, the tumor tissues were obtained and underwent immunohistochemistry for Gli1 and MGMT expression." (PMID 29225516, 2017). "And the time to experience tumor recurrence was significantly shorter in patients with high BICD1 expression (P=0.000117) than in those with high MGMT expression (P=0.005083)." (PMID 29371945, 2017). "The methylation profile subgroups are related to MGMT promoter methylation, tumor location and patient age and outcome." (PMID 28513547, 2017). "The MGMT promoter methylation status is a determinant of chemosensitivity, whereas increased tumor perfusion is related to efficient drug delivery." (PMID 28732091, 2017). "The 6-O-methylguanine repair capacity by MGMT is reduced and renders tumor cells more sensitive to temozolomide." (PMID 28513547, 2017).
tumor (continued). "In tumor adjacent tissues, the promoter methylation status of ESR2 correlated with that of MGMT (r = 0.704, p = 0.002) and in tumor-distant tissues, the methylation status of APC correlated with that of ABCB1 (r = 0.756, p < 0.001)." (PMID 28403857, 2017). "Twenty patients had tumor tissue available for MGMT staining, of whom 12 had low and 8 had intermediate-high expression." (PMID 29262620, 2017). "MGMT greatly improves tumour cell resistance to alkylating nitrosoureas and methylating agents by repairing alkylating lesions in DNA." (PMID 29026176, 2017). "We evaluated the use of novel anti-MGMT oligonucleotides (AMONs) developed on a neutral morpholino backbone that can effectively silence MGMT both in vitro and in tumor models." (PMID 28752860, 2017). "The current analyses comprising all eligible articles revealed that promoter methylation of the p16, CDH1, RUNX3, MLH1, RASSF1A, p15, APC, GSTP1, Reprimo, and MGMT was significantly higher in blood samples of patients with GC compared with non-tumor controls." (PMID 29100425, 2017). "Patient 5, a 69 year-old man with a recurrent GBM (IDH1/2 wild type, methylated MGMT promoter), had tumor progression on a clinical trial consisting of IMRT/TMZ, then TMZ and vorinostat (a histone deacetylase inhibitor)." (PMID 29113409, 2017). "Subjects who had the greatest benefit are those with young age, good performance status, maximal safe resection, and a MGMT methylated tumor." (PMID 28978064, 2017). "It has been shown that the expression of MGMT in tumor cells can be increased, demonstrating BC resistance against chemotherapy, and can be decreased (due to methylation of MGMT promoter), providing the possibility of “cancer” cells enter into apoptosis." (PMID 29209407, 2017). "EG22 is designed to induce the same types of DNA adducts as TMZ, which is inactive against tumours expressing MGMT, the sole human enzyme capable of repairing the O6-methylguanine adduct." (PMID 28800752, 2017). "The current work features a new type of DNA damaging agent with enhanced potency against BRCA1/2 mutants and MGMT-proficient tumour cells." (PMID 28800752, 2017). "A multivariate Cox regression analysis revealed that the Karnofsky performance score, O-6-methylguanine-DNA-methyltransferase (MGMT) promoter methylation, and signs of early tumor progression are prognostic markers of overall survival." (PMID 28101701, 2017). "KPS (p = 0.005), MGMT promoter methylation (p < 0.0001) and early tumor progression (p = 0.001) were revealed to be significant markers." (PMID 28101701, 2017). "Less MGMT proteins are generated by tumor cells with a methylated MGMT promoter, so the patients can benefit more from TMZ." (PMID 28272232, 2017). "All patients diagnosed with PSP had a methylated MGMT promoter whereas the MGMT promoter was methylated in 80% (8 of 10) in patients with true tumor progression." (PMID 28030820, 2017). "Surgical tumor samples were histopathologically analyzed for immunoexpression of MGMT, MSH6 and MIB-1." (PMID 28900805, 2017). "We further demonstrate the feasibility of using a non-ablative dose of radiation in vivo to guide and enhance the delivery of intravenously administered AMONs to achieve 50% MGMT knockdown only at radiation-primed tumor sites in a subcutaneous tumor model." (PMID 28752860, 2017). "MGMT mRNA levels were reduced in tumour samples in comparison to healthy mucosal tissues, and this reduction was seen in 73% of patients." (PMID 28903334, 2017).
tumor (continued). "The time to experience a new tumor event was significantly shorter in patients with high BICD1 expression (P=0.000127) than in those with high MGMT expression (P=0.008955)." (PMID 29371945, 2017). "Our proposed tumour suppressors include genes previously suggested to play a role in oncogenesis (e.g., MGMT and USP44), as well as novel candidates (e.g., KIAA1551, CASP3, and MAFTRR)." (PMID 29089486, 2017). "The results of our study indicate that there was an inverse correlation between the methylation of MLH1 and MGMT in cancer tissues when the tumor was located in the lower third of the stomach (coefficient, –0.48; p = 0.01)." (PMID 26810771, 2016). "In the case of OBG, a phase I clinical trial has defined the maximum tolerated dose of a single dose of TMZ when combined with OBG and has determined the dose of OBG that depletes tumor MGMT activity for 48 h." (PMID 27486975, 2016). "If MGMT expression is low, DNA damage would result in the G/C to A/T transition, oncogene activation, and tumor formation." (PMID 27893664, 2016). "Though on the tumor samples of patient the detection test of MGMT methylation was positive, we think that this result cannot be due only to the action of the alkylating drug, but needs immunological implications of the chemotherapy." (PMID 27142424, 2016). "For MGMT a similar distribution in the core and periphery was found for all tumor grades and subtypes." (PMID 27171431, 2016). "Recent reports demonstrate promoter methylation of tumor-related genes, including MGMT, CDKN2B and RASSF1." (PMID 26675260, 2016). "A previous study has shown that CRC patients who received oral fluorouracil-based adjuvant chemotherapy had a low recurrence rate when the tumor revealed methylation in its MGMT promoter." (PMID 27643594, 2016). "Methylation of the CpG islands located in the promoter region of MGMT is primarily responsible for the inactivation of MGMT in several tumor types." (PMID 27643594, 2016). "The current data show that NR-1 can measure MGMT directly from lysates from multiple tumor cell lines in a timescale of minutes with only 50 nM probe." (PMID 27035132, 2016). "On the other hand, temozolomide alone was sufficient to reduce tumor growth in NCI-H1092 (low MGMT) xenograft." (PMID 27708213, 2016). "To date, however, there are limited data demonstrating the depletion of MGMT activity in tumor tissue exposed to temozolomide." (PMID 27142424, 2016). "The presence of the MGMT enzyme prevented the apoptosis of tumour cells and suppressed the progression of both TMZ and ACNU." (PMID 27458167, 2016). "It is well established that high MGMT activity in tumor cells confers resistance to alkylating agents." (PMID 27035132, 2016). "Our meta-analysis was unable to find any statistical significance between HCC tumor tissues and adjacent tissues for the methylation of the remaining four genes, including MGMT, DAPK1, IGF2 and RB1." (PMID 27835605, 2016). "Some studies reported that MGMT promoter methylation frequency was higher in GC than in non-tumor samples." (PMID 27824946, 2016). "Further limitations in MGMT status determination are the heterogeneity of the tumor and contamination of the tumor sample with normal cells." (PMID 27158275, 2016). "Silencing of a tumor’s MGMT gene by hypermethylation of its DNA promoter region was associated with a GBM and, recently, also an LGA patient’s longer survival in response to temozolomide chemotherapy treatment." (PMID 27798635, 2016). "We found that tumor suppressor genes hypermethylation, represented by MGMT, positively correlated with CagA in clinical specimens, gastric tissues from HP infected C57 mice and GC cell lines transfected by CagA or treated by HP infection." (PMID 26848521, 2016).